MXD1 (MAX dimerization protein 1)
Diseases named in the same sentence as MXD1 in open-access papers (continued):
Sharing a sentence is not in itself a finding about the gene and the disease.
tumor (27 papers, 2008 to 2025). "Further, MXD1 expression was significantly associated with the low proportion of neutrophils in tumor immune microenvironment data which included information from 22 cell types." (PMID 37287538, 2023). "Similar to SIRT1, DNMT3B was stronger associated with Mxd1 in the tumor cell lines." (PMID 29383100, 2017). "Analysis of TCGA data revealed that MXD1 expression was significantly lower in GBM samples compared to non-tumor samples." (PMID 40140670, 2025). "The GEPIA2 analysis results indicate that the top 5 key genes (Bcam, Cdh1, Ifrd1, Mxd1, and Timp1) based on the trajectory analysis of tumor cells can affect the survival of tumor patients." (PMID 38539232, 2024). "MYC-associated factor X dimerization transcription factor 1 (MXD1), a MYC antagonist, is a tumor suppressor and opposes the functions of oncogene MYC." (PMID 37833290, 2023). "The result of apoptosis analysis upon MXD1 overexpression was found conflicting with the anti-tumor effects of HOXA5." (PMID 36167790, 2022). "Up-regulated MXD1 expression inhibits the proliferation of tumor cells stimulated by many factors, such as exogenous Vitamin D3 and Mps1 inhibitors." (PMID 36167790, 2022). "MXD1 overexpression inhibited the proliferation and tumor growth while MXD1 silencing abrogated the HOXA5-mediated proliferation inhibition." (PMID 36167790, 2022). "Intriguingly, HOXA5 overexpression significantly up-regulated the expression of MXD1, a tumor suppressor that can antagonize the formation of MYC-MAX complex, in ECCA cells." (PMID 36167790, 2022). "Among the genes consistently altered in HT29, HCT116, and SW620 cells, 13 genes had previously been reported associated with tumor metastasis, such as BTG2, MXD1, CDKN1A, and HMGA2." (PMID 33791222, 2021). "Higher levels of JUN, MXD1, AQP3 were associated with a better OS, and all three of them were upregulated by deslanoside, suggesting their tumor suppressor role in PCa." (PMID 34830961, 2021). "The PML-RARα fusion protein is not only a misfolded protein by itself, but also promotes aberrant folding of nuclear receptor corepressor 1 (NCOR1), a protein essential for the function of several tumor suppressors, including Max dimerization protein 1 (MAD1)." (PMID 32024211, 2020). "SR9243 also upregulated or downregulated genes associated with tumour proliferation, apoptosis, angiogenesis, invasion and migration, such as ANGPTL4, PDGFR, DUSP5, MMP7, FOXQ1 and MXD1 26–31." (PMID 31138790, 2019). "Our results suggest the possibility that the enhanced expression of Mxd1 suppresses ileal-tumor initiation in Apc Id2 mice." (PMID 26163528, 2015). "It is therefore possible that Mxd1 contributes to the tumor initiation of various tissues including ileum." (PMID 26163528, 2015). "Five miRNAs (19b, 29a, 29b, 29c and 148a) shared 70 predicted targets, some of which (CDK6, PTEN, IGF1, FRS2, PDGFRA, PIK3R1 and MXD1) regulate cellular proliferation and tumor suppression." (PMID 20949028, 2010). "Collectively, these data imply that MXD1 may also be a tumor suppressor to inhibit the proliferation of ECCA cells." (PMID 36167790, 2022). "Reports supporting the important role of the inhibition of the Mxd family of tumor suppressors include studies showing that Mxd1 promotes cell cycle arrest and differentiation; also, several studies showed deletion of the 10q24-q25 chromosome, where the MXD2 gene is located in solid tumors." (PMID 30420889, 2018). "Moreover, Mxd1 repression was reversed after treating tumor cell lines with the demethylating agent 5-Aza-2′deoxycytidine." (PMID 29383100, 2017).
tumor (continued). "This new MXD1 function would be important to curb MYC activity in tumor cells." (PMID 27588501, 2016). "Thus, it is likely that Id2 promotes tumor initiation through inhibition of the Mxd1–Max network and activation of the c-Myc–Max." (PMID 26163528, 2015). "Accordingly, HOXA5 may regulate MXD1 expression in a tumor origination-dependent manner." (PMID 36167790, 2022). "MAX behaves as a classical tumour suppressor gene that encodes for the MAX protein, which interacts with the MYC proto-oncogene and the MAX dimerization protein 1 (MXD1) family of proteins; this MYC/MAX/MXD1 network regulates cell proliferation, differentiation and apoptosis." (PMID 33815275, 2021). "We found that SOX21-AS1 might control the expression of MXD1, which was a tumor suppressor gene." (PMID 33897760, 2021). "MXD1 is a tumor suppressor and functions to compete with MYC for interacting with MAX to form a transcription repressor of the MXD1-MAX." (PMID 36167790, 2022). "More importantly, MXD1 silencing abrogated the HOXA5-decreased proliferation and tumor growth of ECCA cells." (PMID 36167790, 2022). "As part of the MYC/MAX/MXD1 network, MXD1 and MYC compete for binding to MAX, so enhanced MXD1 expression suppresses tumor growth, consistent with our finding here." (PMID 34830961, 2021). "We examined several of these tumor suppressors by qRT-PCR including p21, CHOP, SIK1, MXD1 and several others, each of which showed dramatic increases after corin treatment vs. MS-275 treatment, confirming the microarray data." (PMID 29302039, 2018). "Functionally, MXD1 overexpression also inhibited the proliferation and tumor growth of ECCA cells, but did not significantly alter their migration and apoptosis." (PMID 36167790, 2022). "However, relative mRNA expression levels of EPOR and MXD1 were not significantly different between normal and tumor cases." (PMID 34277626, 2021). "Examination of the tumor tissue recovered from mice treated with corin vs. vehicle showed that tumor cells from the corin-treated animals displayed elevated H3K9 acetylation, H3K4 dimethylation, and increased expression of p21, CHOP, and MXD1, consistent with the cell culture experiments." (PMID 29302039, 2018). "Interestingly, some of them function as tumor suppressors (e.g. BCL2L11, MXD1, WWOX, BNIP3L, and DMTF1) or are candidate tumor suppressors having anti-proliferative properties and DNA repair abilities (e.g. LRRC2, RPA4, PPP6R1, SPEN, RAP1GAP and CISH) (see discussion section)." (PMID 26918450, 2016).
cancer (22 papers, 2014 to 2025). A tumor composed of atypical neoplastic, often pleomorphic cells that invade other tissues. "MXD1 is a MYC inhibitor and competes with MAX, a co-activator, with this MYC/MXD1/MAX signaling pathway being implicated in the development of some types of cancer." (PMID 31261609, 2019). "Conversely, elevated MXD1 levels can inhibit cancer cell growth, further highlighting its role in cell cycle regulation and potential relevance to aging." (PMID 40958908, 2025). "In contrast to MXD1 and MXD2, fewer studies have implicated MXD3 in the direct pathogenesis of human cancer and/or tumor suppression." (PMID 35203395, 2022). "CancerSEA, a cancer single-cell functional state atlas, revealed that Mxd1 was closely related to the regulation of apoptosis and DNA repair." (PMID 33537096, 2021). "Indeed, the Ser/Thr kinases Akt, RSK and S6K, which are frequently over-expressed in cancer can directly phosphorylate Mxd1 at S145 and abrogate transcriptional repression by inhibiting DNA binding without disrupting its association with Max." (PMID 35203395, 2022). "However, subsequent studies in human cancers showed that Myc and Mxd1 were often co-expressed and poorly correlated." (PMID 35203395, 2022). "Dual targeting c-Myc/Mxd1 axis has become an important regulatory mechanism in cancer pathogenesis." (PMID 33537096, 2021). "Together, these results show that SIRT1 is triggering MYC target gene expression by inhibiting MXD1 function, which may contribute to cancer phenotype acquisition." (PMID 29383100, 2017). "This is mostly driven by the cancer-related TF MAX whose binding is antagonized by many other bHLH TFs such as MNT, MXD1, and MXD4." (PMID 39013578, 2024). "Mxd1’s function as a TS in vivo was initially tested in a study that knocked out the gene in mice and found there to be no significant increase in spontaneous cancer incidence or other major phenotypes, thereby implying that other members of the Mxd family were functionally redundant." (PMID 35203395, 2022).
infection (4 papers, 2022 to 2023). The state of being infected such as from the introduction of a foreign agent such as serum, vaccine, antigenic substance or organism. "From this comparative analysis, we identified a putative host candidate within the region mapped by mak: MAX dimerization protein 1 (Mxd1), which is known to be upregulated in murine bone marrow-derived macrophages after infection with the hypervirulent Mtb HN878 strain." (PMID 37405387, 2023). "We found cytokines like IFNγ, IL-4, IL-13, IFNβ1, TNFα, and transcriptional regulators such as HIF1α, STAT1, CTCF, TP73, IRF1, MXD1, ATF4, SPI1 mediate macrophage activation upon infection." (PMID 35789215, 2022). "Mxd1 has been shown to be upregulated in murine bone marrow–derived macrophages upon initial infection with the hypervirulent Mtb HN878 strain and to regulate the fitness of murine dendritic cells, yet the function of Mxd1 in response to Mtb has yet to be determined." (PMID 37405387, 2023).
retinopathy (1 paper, 2025). "Taken together, our findings suggested that ubiquitination of METTL14 promotes retinal neovascularization via m6A-modification on MXD1 mRNA in oxygen induced retinopathy." (PMID 40303324, 2025).
MXD1 also shares sentences with these, for which no sentence is quoted: colorectal cancer (2 papers); head and neck cancer (2); head and neck squamous cell carcinoma (2); neuroblastoma (2); acute respiratory distress syndrome (1); breast carcinoma (1); cervical carcinoma (1); COVID-19 (1); cutaneous melanoma (1); esophageal cancer (1); hepatocellular carcinoma (1); intracerebral hemorrhage (1); myeloid leukemia (1); oesophageal adenocarcinoma (1).